BDNF (brain derived neurotrophic factor)
Diseases named in the same sentence as BDNF in open-access papers (continued):
Sharing a sentence is not in itself a finding about the gene and the disease.
cognitive decline (continued). "Previous research has linked cognitive function in older adults to declining volume in the cortico-cerebellar pathways, and so having at least one copy of the Met BDNF allele may help to preserve these brain regions from age-related atrophy and cognitive decline." (PMID 24465375, 2014). "Brain‐derived neurotrophic factor plays an important role in maintaining neuronal health and synaptic plasticity and reduces Aβ accumulation and τ phosphorylation and subsequent cognitive decline." (PMID 41084412, 2026). "Meanwhile, moderate exercise up-regulates brain derived neurotrophic factor (BDNF) levels and restores insulin sensitivity as well as brain insulin signaling, thereby slowing diabetes-related cognitive decline." (PMID 41460428, 2025). "The neural stem cells reversed the cognitive decline in animal models of the disease through secretion of BDNF and nerve growth factor (NGF)." (PMID 40710133, 2025). "This condition contributes to cognitive decline through mechanisms such as reduced neurogenesis and lower levels of critical neurotrophic factors, including brain-derived neurotrophic factor (BDNF)." (PMID 40901496, 2025). "Meanwhile, gut microbial metabolites, such as short-chain fatty acids (SCFAs), can cross the BBB and influence brain function, with evidence suggesting they ameliorate cognitive decline by elevating levels of BDNF and serotonin (5-HT)." (PMID 41470904, 2025). "In terms of cognitive health, regular physical activity promotes neuroplasticity and protects against cognitive decline through the upregulation of neurotrophic factors, notably BDNF and irisin." (PMID 41305665, 2025). "Keywords included combinations of “Western diet,” “cognitive decline,” “cerebrovascular aging,” “neurodegeneration,” “Mediterranean diet,” “neuroinflammation,” “brain-derived neurotrophic factor (BDNF)”, and “4-hydroxynonenal (4-HNE)”." (PMID 40806031, 2025). "For example, flavonoids from Dendrobium officinale flowers alleviated cognitive decline by reshaping the gut microbiota and suppressing microglial activation, which in turn upregulated BDNF and synaptic proteins and improved synaptic plasticity." (PMID 41470904, 2025). "Neuroinflammation, which is quite common in both aging and neurodegenerative disorders, can negatively affect NGF and BDNF signaling, further potentiating cognitive decline." (PMID 40572619, 2025). "In aged rats, BDNF infusion reverses cognitive decline, improves age-related perturbations in gene expression, and restores cell signaling." (PMID 40380033, 2025). "In mice, the overexpression of irisin has been shown to upregulate hippocampal BDNF levels, enhancing neuroplasticity and possibly offering protection against cognitive decline." (PMID 40407975, 2025). "In agreement with previous studies in AD mouse models, we found a positive correlation between decreased levels of BDNF and synaptic/cognitive decline in 5xFAD mice." (PMID 41313510, 2025). "Chronic copper exposure decreased hippocampal BDNF and TrkB and increased apoptotic processes, resulting in a significant cognitive decline." (PMID 40430064, 2025). "Altered levels of BDNF in the circulation and the CSF in AD patients predict future cognitive decline in healthy older subjects." (PMID 40380033, 2025). "As a result, BDNF is an increasing focus of intervention research, with ongoing efforts to identify modulators of its expression to mitigate cognitive decline in AD." (PMID 41302511, 2025). "Together, this imbalance was likely to enhance susceptibility to these pathologies and correlated PAI‐1/BDNF ratio with BBB dysfunction and cognitive decline in AD patients." (PMID 41013670, 2025). "Altered BDNF expression and elevated levels of pro-inflammatory cytokines have been observed in patients with cognitive decline, suggesting an interplay between neuroinflammation and impaired neuroplasticity." (PMID 41155372, 2025).
cognitive decline (continued). "Emerging evidence indicates a bidirectional interaction between BDNF Val66Met polymorphism and DNA methylation: the Met allele may predict hypo- or hypermethylation within exon IX and at distant promoters, potentially shaping individual susceptibility to cognitive decline." (PMID 41009553, 2025). "Brain-derived neurotrophic factor (BDNF) is the principal neurotrophin supporting neuronal survival and long-term synaptic potentiation; reduced BDNF has been linked to cognitive decline and mood disorders." (PMID 40871684, 2025). "Our findings demonstrate that activation of the BDNF/TrkB/mTOR signalling pathway can mitigate the cognitive decline induced by Rep lido in aged mice." (PMID 41318982, 2025). "Brain-derived neurotrophic factor (BDNF) is a critical downstream target of CREB, as it is vital for the survival and function of neurons The cognitive decline in AD is strongly correlated with dysregulation of the CREB-BDNF signaling axis." (PMID 41007261, 2025). "Elevated PAI-1 levels impair the maturation of brain-derived neurotrophic factor (BDNF) in neurons via the c-Jun N-terminal kinases signaling pathway, rendering the brain more susceptible to neurotoxicity and cognitive decline." (PMID 41465437, 2025). "Abelmoschus Manihot Medicus flower extract reversed cognitive decline in mice by elevating hippocampal levels of BDNF/TrkB/GluR1." (PMID 41470904, 2025). "In HD, retention of BDNF transport and signaling were decreased compounding corticostriatal disconnection increasing motor/cognitive decline over time." (PMID 40362507, 2025). "IL-6 has been shown to upregulate brain-derived neurotrophic factor (BDNF), promoting neuroplasticity and potentially reducing the risk of cognitive decline." (PMID 41301508, 2025). "In a longitudinal study assessing memory performance, individuals in the highest decile of BDNF expression showed 48.3% slower rates of cognitive decline than those in the lowest decile, suggesting a potential neuroprotective effect of BDNF." (PMID 41302511, 2025). "The best cutoff values for serum α-klotho, FGF-23, IL-6, TNF-α, BDNF, BMI, and calcium levels for the diagnosis of dialysis-induced cognitive decline were 469.5 pg/mL, 1,264.5 ng/mL, 1.8 pg/mL, 21.1 pg/mL, 20.0 ng/mL, 23.9 kg/m2, and 2.52 mmol/L, respectively." (PMID 40950978, 2025). "Ethanol-induced reductions in BDNF expression are well-documented and contribute to cognitive decline and neurodegeneration." (PMID 41293241, 2025). "In AD, BDNF levels are longitudinally lowered in both plasma and CSF and correlates with cognitive decline and increased hippocampal atrophy." (PMID 40362507, 2025). "Since our previous analyses in the baseline assessment revealed significant APOE*BDNF interactions on cognitive performance, we also explored the presence of gene-gene interactive effects on cognitive decline in the longitudinal dataset." (PMID 41226628, 2025). "Because of this, BFRE has the potential to be a promising strategy to mitigate age-related cognitive decline by safely enhancing BDNF and neuroplasticity in populations unable to tolerate strenuous exercise." (PMID 40757562, 2025). "Reductions in muscle- and brain-derived BDNF have been consistently observed in both experimental models and clinical studies, with lower levels correlating with insulin resistance, cognitive decline, and sarcopenia." (PMID 41305665, 2025). "BDNF-based gene therapy presents a strategy for restoring synaptic function and mitigating cognitive decline in AD." (PMID 40656325, 2025). "Lactate, an exercise-induced myokine, penetrates the blood–brain barrier (BBB) and triggers the BDNF pathway, potentially safeguarding against cognitive decline and neurodegeneration through the SIRT1/PGC1/FNDC5 pathway." (PMID 40426650, 2025). "Conversely, higher BDNF levels in the brain correlate with reduced cognitive decline and enhanced memory and recall abilities." (PMID 39935805, 2024).
cognitive decline (continued). "For example, LBP reduced Aβ deposit burden, prevented cognitive decline, and restored synaptic plasticity in a mouse model of AD partly through enhancing the BDNF/TrkB/CREB pathway in the hippocampus, which were similar with our current results." (PMID 39564756, 2024). "A mediation analysis was performed to examine the indirect effect of skeletal muscle on cognitive decline through BDNF." (PMID 38559694, 2024). "The mean BDNF level of the cognitive decline group was 2313.46 (1039.42-3592.56) pg/mL, while the level in the cognitively unchanged group was 3182.87 (2343.05-4459.37) pg/ml (P = 0.001)." (PMID 38559694, 2024). "Synaptic plasticity plays a pivotal role in AD, with research indicating lower levels of BDNF in both blood and brain in AD patients and linking higher levels of brain BDNF with slower cognitive decline in elderly individuals." (PMID 39372928, 2024). "BDNF expression was also preserved by Trolox treatment, suggesting a role of this antioxidant in counteracting the cognitive decline induced by weightlessness." (PMID 38512830, 2024). "Elevated astrocytic BDNF can increase the efficacy of astrocytes in supporting AHN and countering AD deficits, while exogenous BDNF supplementation combined with independent enhancement of AHN can attenuate cognitive decline in AD." (PMID 38971770, 2024). "This increase in BDNF fosters improved neuronal development, enhances learning and memory capabilities, and helps prevent cognitive decline." (PMID 39935805, 2024). "Inhibition of NF‐κB can reduce the expression of pro‐inflammatory cytokines (such as IL‐6, IL‐1β, and TNF‐α) and increase the expression of BDNF, thereby ameliorating the cognitive decline of diabetic mice." (PMID 37864452, 2024). "Reduced levels of NGF and/or BDNF can thus lead to pathological situations such as reduced synaptic function, reduced neurotrophic support, and cognitive decline." (PMID 39204102, 2024). "PACAP is suggested to prevent cognitive decline via promoting protein expression of BDNF that participates in neuronal plasticity and essential for learning and memory." (PMID 39931196, 2024). "A likely common mechanism in each of these neurodegeneration and cognitive decline models was the reduction in BDNF." (PMID 39696694, 2024). "While the effect of skeletal muscle on BDNF was evaluated for the indirect or direct effect of skeletal muscle on cognitive decline was evaluated for c’ and c (all P < 0.05)." (PMID 38559694, 2024). "The elevation of BDNF in microglia by treatment with the mixture contributes to the prevention of cognitive decline because BDNF is majorly involved in neuroplasticity and the formation of learning and memory." (PMID 38726426, 2024). "Higher serum brain derived neurotrophic factor (BDNF) levels have been linked to a reduced risk of developing dementia and with a slower cognitive decline with the strongest effects in individuals with higher amounts of AD pathology." (PMID 38589893, 2024). "Another well-known mechanism that occurs in mood disorders and cognitive decline is the reduction of brain-derived neurotrophic factor (BDNF) levels, inducing neuronal plasticity dysfunction and decreased neurogenesis." (PMID 37170283, 2023). "First, we found that BDNF concentration decreases significantly in samples derived from participants with insomnia alone (Group 2) and with the combination of insomnia and cognitive decline (Group 4)." (PMID 37108547, 2023). "In this study, using a female mouse model of ADR-induced cognitive decline, we tested the impact of riluzole (RZ), an orally active BDNF-enhancing medication that is FDA-approved for amyotrophic lateral sclerosis." (PMID 36720792, 2023). "In previous studies, a correlation was found in COVID-19 patients between low BDNF presence and neurological or cognitive decline." (PMID 36831321, 2023).
cognitive decline (continued). "The direct effect of vitamin D and BDNF on cognitive decline and the indirect effect mediated by BDNF was evaluated using path analysis, with the estimation of standardized coefficients." (PMID 36629701, 2023). "The outcome is cognitive decline evaluated by the Mini-Mental State Examination, the exposure is vitamin D, and BDNF is the mediator." (PMID 36629701, 2023). "Previous studies showed that neurotrophin signaling, especially BDNF, imposes a neuroprotective ability in neurons and can contribute to the amelioration of cognitive decline in AD44,63." (PMID 37429840, 2023). "Exercise and dietary restriction elevated the expression of PGC-1α and BDNF, which contributed to enhancing brain function and improving cognitive decline." (PMID 36999158, 2023). "Deacetylation of PGC-1α upregulates the synthesis and secretion of BDNF, a beneficial factor of brain function, to inhibit cognitive decline." (PMID 36999158, 2023). "Overall, our results point to insomnia as a proper intervention to prevent cognitive decline by means of bringing BDNF to homeostasis in an aged population." (PMID 37108547, 2023). "Once we classified the participants into the corresponding group, we aimed to determine the effect of insomnia and cognitive decline alone or combined on the proBDNF (the precursor of mature BDNF) content." (PMID 37108547, 2023). "Oral administration of B. longum NK46 or L. plantarum C29 increases cognitive decline in Ag and Tg mice by inducing NF-κB-mediated BDNF expression." (PMID 36771498, 2023). "The fundamental mechanisms of how exercise impacts BDNF and cognition are not yet fully understood but are a prerequisite to developing new biomarkers and therapies to delay or prevent cognitive decline." (PMID 38002258, 2023). "Brain-Derived Neurotrophic Factor (BDNF), a factor related to brain aging and histone methylation, is also involved in cognitive decline by regulating the adaptability of the hippocampal synapses." (PMID 38139167, 2023). "It has also been suggested that exercise prevents Aβ accumulation and promotes brain‐derived neurotrophic factor expression, thereby inhibiting cognitive decline." (PMID 37334441, 2023). "We previously reported that inhibition of AHN played an important role in cognitive decline 4 weeks after sevoflurane exposure in aged mice through the BDNF/TrkB and NT-3/TrkC pathways." (PMID 37798730, 2023). "As chemotherapy can be neurotoxic, it is postulated that the effects of chemotherapy on BDNF expression can persist long after the completion of chemotherapy and in cancer survivors, resulting in persistent cognitive decline post-chemotherapy." (PMID 36720792, 2023). "The results of the present study additionally indicated a negative correlation between cognitive functions and BDNF plasma concentrations, suggesting higher BDNF levels in subjects with more pronounced cognitive decline." (PMID 36979505, 2023). "We found a similar association between insomnia alone and Group 4 (the combination of insomnia and cognitive decline) and BDNF concentration." (PMID 37108547, 2023). "Accumulating evidence suggested that BDNF/proBDNF imbalance also impacts a variety of neurological diseases aside from cognitive decline." (PMID 35370607, 2022). "In addition, neurotrophic factors such as BDNF and several neurotransmitters such as brain serotonin, norepinephrine, and dopamine are produced as metabolites by the gut microbiota; thus, dysbiosis may cause cognitive decline." (PMID 35719088, 2022). "Parallel studies in postmortem human prefrontal cortex revealed AD subjects had downregulated BDNF signaling and concomitant upregulated cortisol pathway activation, which correlated with cognitive decline." (PMID 35733193, 2022). "Evidence attributes this effect to NGF-β and BDNF overexpression to confer neuroprotective for the central nervous system, thereby mitigating cognitive decline." (PMID 36248655, 2022).
cognitive decline (continued). "Among the elderly with normal cognition, those who carry BDNF Val66Met will experience faster cognitive decline and greater hippocampal atrophy." (PMID 35090576, 2022). "Further, cytochrome c oxidase subunit Va (COX5A) in the hippocampus plays a critical role in age-related cognitive decline through the regulation of BDNF/ERK1/2 signaling pathway." (PMID 36406589, 2022). "We found that long-term administration of buckwheat whole flour (BWF) suppresses cognitive decline by increasing hippocampal BDNF production in SAMP8 mice." (PMID 35807886, 2022). "In this review, we discuss the effect of BDNF on AD-related pathologies, including Aβ accumulation, tau phosphorylation, neuroinflammation, neuronal apoptosis, and cognitive decline." (PMID 35090576, 2022). "Collectively, these findings indicate the protective role of BDNF against cognitive decline with normal aging." (PMID 35887075, 2022). "This study’s strength is that, to our knowledge, it is the first to evaluate the relationship between BB- DNA, plasma BDNF levels, peripheral inflammatory status, and the progression of cognitive decline in MCI and AD patients." (PMID 36613538, 2022). "Further analysis showed that the relationship between AD pathology and the rate of cognitive decline differed due to the level of BDNF expression." (PMID 35814950, 2022). "A decrease in hippocampal BDNF results in cognitive decline and depressive-like state, whereas hippocampal BDNF recovery through several methods, including regular exercise, drug administration, and transgenic modification, restores cognitive function." (PMID 35600989, 2022). "The rate of cognitive decline was negatively correlated with the level of BDNF expression in the brain." (PMID 35814950, 2022). "We also review the therapeutic approach for cognitive decline by the upregulation of the endogenous BDNF/TrkB-system." (PMID 35887075, 2022). "Multiple logistic regression estimating the odds of subsequent cognitive decline between baseline and follow-up visits as a function of quartiles of serum BDNF at baseline*." (PMID 34239422, 2021). "The defense in the mouse hippocampus from scopolamine-induced damage through as brain-derived neurotrophic factor-mediated Nrf2 activation was established by the use of quercetin by diminishing cognitive decline." (PMID 34206761, 2021). "The C29 supplementation (DW2009, C29-fermented soybean) alleviates cognitive decline with high blood BDNF levels in individuals with mild cognitive decline via the modulation of the microbiota-gut-brain axis." (PMID 34579150, 2021). "In our previous study, the association between the BDNF rs6265 and cognition in veterans with PTSD was detected, showing a significant cognitive decline, evaluated using the ROCF test scores, in carriers of the A allele compared to G allele carriers." (PMID 33926045, 2021). "Diagnosis (p < 0.001), BDNF rs56164415 (p = 0.011) and smoking (p = 0.028) were significant predictors of the cognitive decline in subjects with PTSD." (PMID 33926045, 2021). "Regarding BDNF, high BDNF expression has been reported to slow the rate of cognitive decline and propolis promotes its production in SH-SY5Y cells." (PMID 33680059, 2021). "This warrants further research to evaluate the added-value of serum BDNF in health promotion initiatives directed toward cognitive decline prevention in community-dwelling older adults." (PMID 34239422, 2021). "Regarding the MoCA-J executive function subscale, the odds of cognitive decline from baseline to the follow-up visit was substantially lower among those with highest than lowest baseline BDNF levels; i.e., OR: 0.27 (95% CI: 0.13–0.60; p-value = 0.001)." (PMID 34239422, 2021). "In contrast, diets rich in saturated fatty acids and total fat are related to lower brain levels of brain-derived neurotrophic factor (BDNF),to neuronal plasticity, and to cognitive decline." (PMID 33730037, 2021).